KRAS (KRas proto-oncogene, GTPase)
Diseases named in the same sentence as KRAS in open-access papers (continued):
Sharing a sentence is not in itself a finding about the gene and the disease.
cervical carcinoma (continued). "The Cancer Genome Atlas (TCGA) Research Network has identified high frequencies of ARID1A, KRAS, and PTEN mutations in endometrial-like cervical cancers." (PMID 36397138, 2022). "In summary, we identified simultaneous mutations in KRAS and SMAD4 in a pre-treatment tumor obtained from a case of stage IB cervical cancer with local recurrence." (PMID 35008475, 2021). "A set of endometrial-like cervical cancers comprised predominantly of HPV-negative tumors and characterized by mutations in KRAS, ARID1A and PTEN was discovered in another study." (PMID 33736612, 2021). "In a recent study in 154 cervical cancers, including 43 ADC, KRAS mutations were almost restricted to ADC patients, whereas PIK3CA mutations were more frequent in SCC." (PMID 33570867, 2021). "We identified simultaneous mutations in KRAS and SMAD4 in a pre-treatment tumor obtained from a case of stage IB cervical cancer with local recurrence." (PMID 35008475, 2021). "EGFR, KRAS and PIK3CA genes were selected to be amplified in specific regions since these genes are implicated in most cancers, especially in cervical cancers." (PMID 33736612, 2021). "Another study on cervical cancer cases of European origin identified PIK3CA, KRAS and FBXW7 to be the most mutated." (PMID 27829003, 2016). "Most studies of KRAS and PIK3CA mutations in cervical cancer have combined PCR amplification across mutation hotspot regions with Sanger sequencing." (PMID 26209091, 2015). "Preclinical data suggest that KRAS-driven signaling may contribute to radio resistance in cervical cancer, although its clinical relevance remains to be fully established." (PMID 41590369, 2026). "KRAS G13D was frequently observed in bowel cancer (14.2%) and cervical cancer (16.0%)." (PMID 40970755, 2025). "Similarly, miR-30c-5p promotes the ferroptosis of cervical cancer by targeting the METTL3/KRAS axis, and inhibits the growth and metastasis of xenografts of cervical cancer." (PMID 38550378, 2024). "In this study, five different genomic regions within the top three most frequently mutated genes (EGFR, KRAS and PIK3CA) in COSMIC database with a key role in the development of cervical cancers were selected to study the mutation frequency in Bangladeshi patients." (PMID 33736612, 2021). "On the basis of these findings, cetuximab therapy may be efficacious in cervical carcinoma patients who have EGFR protein overexpression without KRAS mutations, particularly those who have not responded to standard treatment modalities." (PMID 21730982, 2011). "In cervical cancer, miR-30c-5p targets the METTL3/KRAS axis, fostering ferroptosis and concomitantly suppressing tumor growth and metastasis." (PMID 39551792, 2024). "The expression of seven hub genes in the PI3K/AKT/mTOR pathway were increased in cervical cancer: EIF4EBP1, GSK3B, HRAS, KRAS, NRAS, PIK3CB and PIK3R2." (PMID 36911370, 2023). "A landmark multi-omic analysis by The Cancer Genome Atlas (TCGA) provided a comprehensive molecular characterization of cervical cancer, identifying APOBEC-driven mutagenesis as a dominant process and recurrent alterations in PIK3CA, PTEN, KRAS, ERBB3, CASP8, HLA-A, SHKBP1, and TGFBR2." (PMID 41590369, 2026).
cervical carcinoma (continued). "For example, KRAS mutations, which are present in 45% of EC, 30% of OC, and 20% of cervical cancers, often lead to continuous signaling through the KRAS pathway, even in the absence of upstream growth factor stimulation." (PMID 38920692, 2024). "Our results show that a few alterations of host oncogenes, such as MYC, PIK3CA, MEK1 and KRAS, in conjunction with the episomal form of HPV16, might be sufficient to drive development of cervical cancer." (PMID 36763589, 2023). "Previous research supports this hypothesis that the KRAS/ERK signaling pathway is closely related to OGT levels in pancreatic, gastric, and cervical cancers." (PMID 35387659, 2022). "DNA from 46 cervical cancer tissue samples were extracted and amplified by PCR, using 1 set of primers designed for EGFR and 2 sets of primers designed for two different regions of both PIK3CA and KRAS gene." (PMID 33736612, 2021). "Moreover, key gene mutations, such as phosphatidylinositide 3-kinases catalytic subunit α (PIK3CA), Kirsten rat sarcoma viral oncogene homolog (KRAS), and epidermal growth factor receptor (EGFR), have been observed in cervical cancer patients." (PMID 31709304, 2019). "The KRAS signaling pathway is highly involved in cell proliferation and division; it belongs to the RAS/MAPK pathway, and in the oncogenic context, KRAS has very important effects in the carcinogenesis process of endometrial, colorectal, bladder, breast, and cervical cancer." (PMID 36672296, 2023).
serous carcinoma (64 papers, 2008 to 2025). "More specifically, serous cystadenomas do not have mutations in either KRAS or BRAF in contrast to serous borderline tumors and low-grade serous carcinoma, furthermore, mucinous cystadenomas also has a mutation in KRAS." (PMID 35281584, 2022). "So, we wanted to evaluate the clinical benefit of MEK inhibitors in the management of advanced-stage low-grade serous carcinoma harboring KRAS or NRAS mutation." (PMID 35328764, 2022). "In contrast, PIK3CA and KRAS were altered by mutations in those histological subtypes, in contrast to high-grade serous carcinomas (P = 0.002 and P = 0.0495, respectively)." (PMID 33947352, 2021). "Accordingly, our results showed that CAISMOV24 cell line harbors KRAS mutation, which is relatively frequent in recurrent low-grade serous carcinomas." (PMID 29132324, 2017). "Mutations in either BRAF or KRAS can frequently be seen in low grade serous adenocarcinoma and borderline tumours of the ovary and seem to be mutually exclusive." (PMID 26197800, 2015). "KRAS mutations at codons 12 and 13 occur in one-third of SBTs and in 33% of low grade serous carcinomas." (PMID 24868556, 2014). "For instance, two-thirds of low-grade serous carcinomas carry mutations in KRAS, BRAF or ERBB2 (refs 17, 18, 19)." (PMID 23839242, 2013). "At the molecular genetic level, low-grade serous carcinomas are characterized by frequent somatic sequence mutations in genes that are involved in signal transduction including KRAS, BRAF, ERBB2, and PIK3CA." (PMID 22028712, 2012). "In low-grade ovarian serous carcinomas, estimated 27% to 54% of cases harbor mutations in KRAS oncogene, whereas in high-grade serous carcinomas, mutation rate of KRAS ranges from 0 to 12%." (PMID 23554638, 2010). "We reported earlier that KRAS or BRAF mutations were quite common in low-grade serous ovarian carcinomas but rare in conventional high-grade serous carcinomas." (PMID 19018267, 2008). "Our present results showing low frequencies of either KRAS or BRAF mutations in conventional high-grade serous carcinoma are consistent with our earlier reports." (PMID 19018267, 2008). "BRAF and KRAS mutations are common in serous borderline tumors and low-grade serous carcinomas, but very rare in most serous carcinomas of high-grade." (PMID 19025622, 2008). "Nevertheless, a significant difference is observed for the KRAS exon 12 mutation status (p = 0.007), with 77.1% (37 cases) of high-grade serous carcinoma patients having a mutant allele, compared to 95.9% (47 cases) among those with other malignant epithelial tumors." (PMID 38390896, 2024).
serous carcinoma (continued). "Low-grade serous ovarian carcinoma exhibits a unique genetic profile characterized by KRAS/BRAF mutations compared to high-grade serous carcinoma, thus MEK inhibitors might be appropriate for the treatment of this malignancy." (PMID 39139644, 2024). "Among the low-grade serous carcinomas, there is a high frequency of activating mutations in the KRAS or BRAF genes; however, it remains unclear as to how these mutations contribute to tumor progression." (PMID 27128903, 2016). "Molecularly, low-grade serous carcinomas generally have low levels of chromosomal instability and carry frequent mutations in KRAS, BRAF, and ERBB2, while high-grade serous carcinomas tend to have high levels of chromosomal instability and frequently show mutations in TP5310." (PMID 25314936, 2015). "The inverse association between KRAS mutation and PR expression found here is in line with previous studies demonstrating a higher expression of ER and PR in low-grade serous carcinomas, although the number of KRAS-mutated serous tumours in our study was too low to make any direct comparisons." (PMID 23800114, 2013). "Similar but different BRAF and KRAS mutation roles in oncogenesis generate potential implications for the treatment of invasive mucinous ovarian carcinoma and highlight a challenge in its response to conventional chemotherapy compared to high-grade serous carcinomas." (PMID 38391958, 2024). "There has been sufficient evidence to support that low-grade serous carcinoma (LGSOC) is distinct from high-grade serous (HGSOC) and is associated with BRAF and KRAS mutations." (PMID 39941911, 2025). "The mutation of KRAS/BRAF was observed in Western countries, whereas PIK3CA mutation was the main driver for Japanese low-grade serous carcinoma progression." (PMID 35621684, 2022). "The estimated cumulative risk of developing serous carcinoma is lowest in the BRAF-mutated group, with the 10-year risk being 0.5% compared to 4.4% for wildtype and 2.3% for KRAS-mutated SBTs." (PMID 31839880, 2019). "About 50% of mucinous tumors have KRAS mutations and 20% HER2 amplification, higher than with serous carcinomas, and both markers generally seem associated with better survival and fewer recurrences [31,]." (PMID 31005287, 2019). "KRAS and BRAF mutations are found in a proportion of low-grade serous carcinomas and, frequently, they are mutually exclusive." (PMID 29132324, 2017). "Mutually exclusive KRAS and BRAF mutations are observed in ~65% of SBTs but are rarely seen in high-grade serous carcinomas." (PMID 19746182, 2010).
serous carcinoma (continued). "Presence of KRAS and BRAF mutations was significantly more common in serous borderline ovarian tumors as compared to serous carcinomas (p = 0.0221; KRAS mutations) and (p < 0.0001; BRAF mutations); data not shown)." (PMID 19638206, 2009). "Notably, 13 (46.4%) of these fallopian tube samples were derived from patients diagnosed with serous carcinoma, all of which were also being KRAS wild-type." (PMID 23800114, 2013). "In this study, KRAS mutation status was not a prognostic factor in serous carcinomas, but, notably, the vast majority of tumours in this histological subgroup were KRAS wild-type." (PMID 23800114, 2013). "The significantly higher frequency of KRAS/BRAF mutations in non-serous type carcinomas compared with conventional high-grade serous carcinomas in this study is a finding of great interest." (PMID 19018267, 2008). "Interestingly, in a previous study, KRAS (but not BRAF) mutation in ovarian serous borderline tumor is associated with recurrent low-grade serous carcinoma." (PMID 27128903, 2016). "On the other hand, KRAS mutation does not seem to play a major role in high grade serous carcinoma." (PMID 19358724, 2009). "Furthermore, epigenetic changes may be an important event in the carcinogenesis of some low grade serous carcinoma without KRAS or BRAF mutation." (PMID 27128903, 2016). "Unlike high-grade serous carcinoma, MOC is characterized by unique molecular features—including frequent KRAS mutations and HER2 amplifications—and exhibits limited sensitivity to platinum-based chemotherapy." (PMID 40427025, 2025). "Low grade serous carcinomas are driven by BRAF and KRAS and represent <5% of ovarian tumors." (PMID 38352443, 2024). "After adjusting for age and stage, the risk of subsequent serous carcinoma was lower for SBTs harboring BRAF (HR 0.27, 95% CI 0.08–0.93), but not KRAS (HR 1.00, 95% CI 0.45–2.23) mutations, in comparison to wildtype SBTs." (PMID 31839880, 2019). "Together, KRAS or BRAF mutations are present in 68% of low-grade serous carcinomas, whereas they have not been identified in high-grade serous carcinoma." (PMID 23554638, 2010). "GSEA pathway analysis of those 26 neoplasms demonstrated that the G2M checkpoint pathway, E2F transcription factors, and KRAS downstream signaling were upregulated compared to fusion-negative, low grade serous carcinomas of the ovary, fallopian tube, or peritoneum." (PMID 39575425, 2024).
serous carcinoma (continued). "Furthermore, the frequency of KRAS and BRAF mutations in Japanese individuals with low-grade serous carcinomas is not known." (PMID 27128903, 2016). "This revealed that KRAS mutation was associated with a significantly improved OCSS in endometroid carcinomas (p = 0.012), while KRAS mutation status was not a prognostic factor in mucinous or serous carcinomas." (PMID 23800114, 2013). "The RAS-MAPK signaling pathway (genomic alterations of NF1 at 16% and KRAS at 12% with mutual exclusivity), the PI3K-mTOR pathway (PIK3CA at 12% and TSC2 at 8%), and certain receptor tyrosine kinases (ROS1 at 9% and ERBB2 at 8%) might be candidates for targeted therapy in serous carcinomas." (PMID 38201563, 2023).